TLR4 (toll like receptor 4)
Diseases named in the same sentence as TLR4 in open-access papers (continued):
Sharing a sentence is not in itself a finding about the gene and the disease.
diabetes (continued). "We found that diabetes significantly resulted in increased expression of RAGE, TLR4 and MMP9 in damaged arteries which also correlated with intracranial formation of aneurysms." (PMID 23844137, 2013). "Innate immune receptors TLR4 and RAGE and their endogenous ligands such as high mobility group binding protein HMGB1 and S100 calgranulins are reported to be upregulated in diabetes." (PMID 22474421, 2012). "In this study, we further support our previous findings by showing that the expressions of TXNIP, pro-inflammatory IL-1β, iNOS, and pattern recognition receptors TLR4 and P2X7R in the retina are elevated at 4 weeks of diabetes." (PMID 22474421, 2012). "For example, MSC-sEVs derived let-7b inhibited TLR4 expression, thus reducing the downstream activation of MKK3/6 and decreasing p38 phosphorylation, while miR-21 delivered by MSC-sEVs downregulates p38 MAPK to modulate β-cell apoptosis in diabetes." (PMID 41209696, 2025). "First, while our multi-timepoint design captured dynamic molecular changes, clinical comorbidities such as diabetes is known to alter TLR4 expression and apoptotic thresholds were not modeled." (PMID 40520774, 2025). "In NOD mice lacking TLR4, diabetes onset is accelerated, potentially due to altered gut microbiota or impaired regulatory T cell (Treg) function, suggesting an immunoregulatory role for TLR4 in maintaining immune tolerance." (PMID 40969771, 2025). "When compared to the normal group, the diabetes model group's mRNA expression levels for LBP, TLR4, MyD88, NF-κB, AP-1, and IRF-3 were significantly higher (p < 0.05); after taurine treatment, we discovered that these mRNA levels had decreased significantly (p < 0.05)." (PMID 38560269, 2024). "A recent study showed that oxidative stress (ROS and H2O2) promoted the expression of Toll-like receptor 2 (TLR2) and Toll-like receptor 4 (TLR4) in human periphery monocytes to increase the expression of cytokines, such as IFN−gamma, IL−1 beta, IL−6, etc., in diabetes mellitus (DM)." (PMID 37175958, 2023). "In addition, the expression of TLR4 mRNA and the protein levels TNF-α were increased in the spinal cord of streptozotocin-induced diabetes." (PMID 36946851, 2023). "Finally, TLR2- and TLR4-induced expression of immunomodulatory effectors Cox-2 and IDO was significantly augmented by diabetes." (PMID 34566972, 2021). "Activation of the diabetes-mediated pyroptosis-related inflammasomes, such as nucleotide-binding oligomerization domain-like receptor protein 3 (NLRP3), Toll-like receptor 4 (TLR4), caspase-1, interleukin (IL)-1β, and the IL-18 axis, plays an essential role in DKD lesions." (PMID 33692782, 2021). "LMWH could decrease inflammatory factors in diabetes by inhibiting the HMGB1-TLR4-NF-κB pathway, which gave rise to our study of the mechanism of interaction of LMWH and TLR4 in acute sinusitis." (PMID 34867331, 2021). "In the absence of diabetes mellitus, cardioprotective EVs have been shown to activate the toll-like receptor 4 (TLR-4)-extracellular signal-regulated kinase 1 and 2 (ERK1/2) pathway." (PMID 32821437, 2020). "Additionally, we scrutinized a large human RNA-Seq dataset of aortic tissue to assess the co-expression of TLR4 and MD2 as well as subunits of the vascular NADPH oxidases under diabetes and hypertension." (PMID 32694567, 2020). "Additionally, we scrutinized a large human RNA-Seq dataset of aortic tissue to assess the co-expression of TLR4, MD2, and subunits of the vascular NADPH oxidases under diabetes and hypertension." (PMID 32694567, 2020). "Our results demonstrate that TLR4 blockade decreases CD4+ T lymphocyte activation and auto-antigen-specific proliferation both in vitro and in vivo, decreases the infiltrative insulitis and finally prevents the onset of spontaneous diabetes." (PMID 31852918, 2019). "Thus, TLR-4 plays a key role in the onset and progression of atherosclerosis, as well, as in CAD and other inflammatory diseases, such as diabetes." (PMID 30654523, 2019).
diabetes (continued). "In addition, we performed multiple logistic regressions to evaluate the predictive value of serum MMP9 and TLR4 in AAD with the adjustment for age, gender, smoking, drinking, hypertension, diabetes and hyperlipidemia." (PMID 30497388, 2018). "We and others have shown increased pattern recognition receptors, TLR2 and TLR4, in diabetes and have also shown that knockout of TLR2 and/or TLR4 in a mouse model can result in decreased microvascular complications using the streptozotocin- (STZ-) induced diabetes model." (PMID 29435463, 2017). "Induction of diabetes to mice facilitated retinal Il-1β production in Iba-1-positive resident macrophages (i.e., microglia), and AGE stimulation to murine microglial cells upregulated Il-1b expression via Tlr4." (PMID 29170525, 2017). "This suggested the plasma lipid levels, hypertension and diabetes did not influence the effect of TLR4 on CAD." (PMID 27652106, 2016). "In addition, TLR4, another receptor of HMGB 1 induced by diabetes, was also attenuated by supplement of resveratrol." (PMID 27833703, 2016). "In the present study, we utilized a rat model of type 2 diabetes mellitus induced by HFD/STZ and determined whether TGT could suppress the activation of TLR4/NF-κB pathways and thereby attenuate renal tubulointerstitial injury." (PMID 26347890, 2015). "A deficiency of TLR4 but not of TLR2 alleviated albuminuria, tubulointerstitial fibrosis and inflammation induced by diabetes." (PMID 26398934, 2015). "Until recently TLR4 expression in islets has only been examined under normal conditions and not with respect to diabetes development." (PMID 24594974, 2014). "While TLR2 and TLR9 knockout mice show little development of diabetes, a defect of TLR3 appears to be without impact and, as we show here, deficiency in TLR4 causes enhancement of the disease process." (PMID 24086519, 2013). "Compared to animals with wildtype TLR4 expression (TLR4+/+), female NOD mice carrying a homozygous TLR4 defect (TLR4−/−), showed significant acceleration of diabetes development, with a younger age at diabetes onset (TLR4+/+ 177±22 d, TLR−/−: 118±21 d; p<0.01)." (PMID 24086519, 2013). "Total diabetes rates were not significantly different between the groups (TLR4+/+: 71%, TLR4+/−: 67%, TLR4−/−: 80%)." (PMID 24086519, 2013). "TLR4 activation and expression increase in diabetes in response to hyperglycemia, and this was not prevented by insulin treatment." (PMID 22924123, 2012). "In stark contrast to the importance of IL-12 in TLR4 mediated DC maturation and subsequent induction of diabetes, IL-12 was not required in TLR3 mediated DC induction of autoimmunity." (PMID 21931625, 2011). "Thus, administration of the TLR4 agonist LPS and of the TLR9 agonist CpG has been shown to prevent spontaneous diabetes onset in the non obese diabetic (NOD) mouse." (PMID 20628601, 2010). "It is also striking that diabetes protection by TLR3 stimulation required the presence of IL-4 which was not the case for TLR4-induced protection." (PMID 20628601, 2010). "Experimental studies have shown that T2DM patients exhibit a fivefold increase in TLR4 expression in monocytes compared to non-diabetic controls, suggesting that enhanced inflammatory signaling in monocytes may exacerbate diabetes progression." (PMID 40357304, 2025). "Thus, excessive production of mitochondrial ROS elicited by eNAMPT/TLR4 or NAD+ may play a critical role in reducing NO bioavailability and attenuating EDR in CAs in people with diabetes." (PMID 38898303, 2024). "In addition, the function of antigen recognition by the CD163+ monocyte was decreased in individuals with diabetes and complications compared to those without, although a very low proportion of TLR4+ cells was detected in the CD163+ cells from both groups." (PMID 39337580, 2024).
diabetes (continued). "Moreover, the findings suggest that exercise exerts its beneficial effects through the activation of the irisin signaling pathway, which, in turn, inhibits the TLR4/MyD88/NF-κB pathway, thereby mitigating the exacerbation of hippocampal neuroinflammation and the decreases in AHN induced by diabetes." (PMID 39452118, 2024). "Given the critical role of TLR4/TRAF3 in regulating the immune response, it is conceivable that MLGZG might exhibit improved therapeutic efficacy in treating other metabolic diseases, such as diabetes." (PMID 35116066, 2022). "Notably, previous studies demonstrated that ISO inhibits TLR4 activation during ischaemic stroke in patients without diabetes." (PMID 35419168, 2022). "For example, increased circHIPK3 stimulated the activation of the TLR4 pathway and NLRP3 inflammasome and the production of pro-inflammatory cytokines (e.g., TNF-α, IL-1β) in gouty arthritis whereas its silencing alleviated inflammatory damage in myocarditis and diabetes mellitus." (PMID 36072601, 2022). "A high level of Toll-like receptor 4 (TLR4) and phosphorylated p65 subunit of NF-κB (phospho-NF-κB p65) was observed in the untreated diabetes (DM) group." (PMID 33996978, 2021). "When exploring whether diabetes aggravates I/R-induced AKI in rats, some results have shown that diabetes aggravated oxidative stress, inflammatory response, and apoptosis after renal I/R by enhancing TLR4/NF-κB signaling and blocking the Nrf2/HO-1 pathway." (PMID 35186957, 2021). "Considering that diabetes is a progressive disease, especially in non-treated animals, it is reasonable to speculate a time dependency in the expression levels of TLR4 in this tissue." (PMID 32694567, 2020). "However, inhibition of TLR2 or TLR4 in diabetes exhibited reduced inflammatory responses, indicating that TLR2 or TLR4 might mediate HMGB-1-induced inflammation in DN." (PMID 27847406, 2016). "Thus, we propose a mechanism that, in the early stage of diabetes, a leakage of albumin into the renal tubules upregulates TLR2 and TLR4 and induces HSP70 release and TLR4 activation, leading to a more severe injury and a stronger inflammatory response in the tubule and interstitium." (PMID 26398934, 2015). "As the expression of TLR4 showed to be independent of diabetes and showed a negative correlation with age, i.e. progression of the diabetes in the systemic compartment, the capacity to respond to TLR4 was measured by monitoring cytokine levels after LPS challenge at various ages of the mice." (PMID 24594974, 2014). "Therefore, it is an interesting observation that although a direct activation of insulin-producing beta cells via TLR4 impairs their function, the absence of TLR4 results in an acceleration of diabetes development." (PMID 24086519, 2013). "Due to collection of circulating PBMCs only in a sub-set of the participants, there were not enough participants within the diabetes CTCA subgroup to analyze for gene expression of CD14 and TLR4 in circulating PBMCs." (PMID 39563343, 2024). "Diabetes did not alter the expression of HMGB1 and HSP70 in the adrenal glands of Swiss-Webster mice; however, it increased the expression of TLR4 and TRIF compared to non-diabetic mice." (PMID 40496562, 2025).
breast cancer (271 papers, 2010 to 2026). A primary or metastatic malignant neoplasm involving the breast. "TLR4 overexpression in tumors is often associated with chemoresistance to paclitaxel, a drug used in neoadjuvant chemotherapy regimens for breast cancer and tumor growth." (PMID 40647480, 2025). "Although TLR4 is associated with poor prognosis in patients with breast cancer, its activation in microglia can effectively reduce the degree of brain invasion of breast cancer cells." (PMID 40727252, 2025). "Further research is imperative to comprehensively understand the mechanisms underlying TLR4 involvement in breast cancer and to systematically explore its therapeutic potential in vivo." (PMID 38903515, 2024). "We also analyzed the associations between TLR4 expression and the molecular subtype of breast cancer." (PMID 38463226, 2024). "Surprisingly, we also observed that a high level of TLR4 was significantly associated with a better survival probability of basal subtype of breast cancer patients." (PMID 33969603, 2022). "As opposed to cyclin D1a, the overexpression of cyclin D1b variant was observed in breast cancer tissues compared to normal breast tissues, which characterizes metastasis and invasive migration of cancer cells mediated by αvβ3 and toll-like receptor 4 (TLR4)." (PMID 35327956, 2022). "High-level expression of Toll-like receptor 4 (TLR4) is associated with poor overall survival of epithelial ovarian cancer patients and metastasis of breast cancer." (PMID 36132137, 2022). "TLR4-deficient mouse intriguingly showed pro-tumor effect in skin, lung, and mammary cancers, which determined that loss of TLR4 signaling pathway impaired anti-tumor immunity." (PMID 34718325, 2021). "Previous studies have shown that TLR4/MyD88/NF-κB pathway is linked to the inflammatory response in hepatocellular carcinoma, breast cancer, and tumor-associated macrophages (TAMs) on Ishikawa cells." (PMID 33849528, 2021). "As one of the most unique TLRs, TLR4 has already been linked to tumors including breast cancer and has been implicated in low overall survival rate." (PMID 33733435, 2021). "In previous research, we have found that TLR4 was linked to the metastasis of breast cancer in vitro and in vivo by activating the TLR4/MyD88/NF-κB signaling pathway." (PMID 34475958, 2021). "NFκB activation, a direct effect of TLR4/7 stimulation, has been implicated in breast cancer initiation and progression." (PMID 34299224, 2021). "An increased TLR4 expression has been associated with tumor size and distant metastases in breast cancer, a higher recurrence rate in prostate cancer, and a poorer overall survival rate in ovarian cancer." (PMID 32424768, 2020). "The authors showed that TLR4 expression on DCs is necessary for efficient antigen presentation as breast cancer patients with germline TLR4 loss-of-function allele relapsed faster after chemo- or radiotherapy than those with normal TLR4 alleles." (PMID 31695691, 2019). "In the subgroup of tumor type, the combined analysis indicated that the increased expression of TLR4 was significant associated with a poor DFS in breast cancer (HR = 1.18, 95% CI (0.60, 2.32); P < 0.001)." (PMID 29560134, 2018). "Particularly, it has been shown that LPS/TLR4 has critical role in stimulation of invasiveness of breast cancer cells, and status of TLR4 expression is deeply linked to metastasis." (PMID 28212583, 2017). "A TLR4 single-nucleotide polymorphism reduces the interaction between HMGB1 and TLR4 thereby inhibiting antigen presentation which is associated with a poor prognosis of breast cancer patients." (PMID 26948869, 2016). "High level of TLR4 expression was found to be associated with increased incidence of metastasis and poor prognosis in breast carcinoma, colorectal cancer and hepatocellular carcinoma." (PMID 26675260, 2016).
breast cancer (continued). "TLR signaling has been implicated in breast cancer progression, as TLR4 is expressed at high levels on invasive breast cancer cells and knock-down of TLR4 leads to reduced cell proliferation and survival." (PMID 26106384, 2015). "This immune activating pathway plays a significant role in the prognosis of breast cancer because patients carrying a TLR4 loss-of-function allele relapse more quickly." (PMID 25755254, 2015). "Studies in mouse models show that cyclophosphamide is less effective against HMGB1-negative tumors, and that human breast cancer patients carrying a TLR4 loss-of-function allele have a poor prognosis." (PMID 25755254, 2015). "Clinical studies in breast cancer have showed that a correlation exists between the presence of a single nucleotide polymorphism in the TLR4 gene, which prevents the binding of HMGB1 to TLR4, and early relapse after anthracycline treatment." (PMID 24432020, 2014). "They suggested that the variants of ERCC2, TLR4, IL-2, IL-6, and IL-21 genes had associations with breast cancer prognosis respectively." (PMID 25075970, 2014). "In breast cancer, data shows that patients who express the TLR4 loss of function allele experience a relapse more rapidly, following radiotherapy and chemotherapy, when compared with those patients who express the normal allele." (PMID 24959291, 2014). "Breast cancer patients harboring the loss-of-function Asp299Gly polymorphism of TLR4 relapsed earlier after receiving anthracycline-based chemotherapy." (PMID 24904578, 2014). "Mutation of TLR4 gene in humans was found to have an increased frequency of metastasis in breast cancer patients." (PMID 23673510, 2013). "The counterpart mutation in TLR4 in mouse models showed a decreased response to both chemotherapy and radiation therapy for mammary cancer." (PMID 23673510, 2013). "Patients with breast cancer who carry a TLR4 loss-of-function allele relapse more quickly after radiotherapy and chemotherapy than those carrying the normal TLR4 allele." (PMID 24216992, 2013). "The authors further showed that breast cancer patients bearing loss-of-function TLR4 alleles had significantly worse prognosis when treated with anthracycline-based chemotherapy." (PMID 22151962, 2011). "In addition, a high level of serum resistin has been reported to be correlated with poor overall survival of patients with breast cancer, which is caused by the activation of Toll-like receptor 4 (TLR4)/NF-κB/STAT3 signaling pathway." (PMID 40863244, 2025). "Additionally, Klebsiella pneumoniae has been implicated in TLR4-mediated inflammation due to its LPS, a pathway that promotes tumor growth, particularly in estrogen receptor-positive (ER+) breast cancer cells (MCF-7)." (PMID 40005832, 2025). "Breast cancer patients with dysfunctional TLR4 alleles experience faster recurrence after radiation and chemotherapy compared to those with normal TLR4 alleles, indicating a close association between TLR4 and anti-tumor immune responses." (PMID 38835772, 2024). "The expression of certain receptors in breast cancer is associated with multiple factors, of which TLR4 expression may be one, however, the findings are still controversial." (PMID 38463226, 2024). "Indeed, the upregulation of TLR4 has been associated with increased breast cancer metastasis and a high proliferative activity and cell senescence of tumors." (PMID 39768151, 2024). "Initially, we thought that S100A8 mainly plays a role in premetastatic niche formation, but several studies have reported that various types of cancer cells also express TLR4 at the cell surface, and that its expression is associated with poor prognosis in breast cancer and other types of cancer." (PMID 36932197, 2023). "Blockade of HMGB1 binding to TLR4 is associated with early recurrence in breast cancer patients." (PMID 37291495, 2023).